RARA (retinoic acid receptor alpha)
Diseases named in the same sentence as RARA in open-access papers (continued):
Sharing a sentence is not in itself a finding about the gene and the disease.
breast carcinoma (97 papers, 1993 to 2025). "It should be emphasized that most breast carcinomas and breast cancer cell lines show loss or down-regulation of RARβ receptor expression, whereas RARα and γ, as well as RXRs, appear to be variably expressed in both normal and tumor cells." (PMID 22418926, 2012). "Both RARα and RARβ have been implicated in the anti-proliferative effects of retinoids against breast cancer." (PMID 20696059, 2010). "Among the genes known to play a relevant role in mammary tumors, BRCA1 (BReast CAncer gene 1) and PALB2 (Partner And Localizer of BRCA2), two breast cancer susceptibility genes whose mutations result in familial cases of the disease, seem to be required for RARα signaling." (PMID 38360674, 2024). "In addition, 23–32% of the human breast cancers characterized by amplification of the ERBB2 gene (the locus encoding the HER2 protein) show co-amplification of the RARα gene (RARA)." (PMID 38360674, 2024). "Moreover, RARα has also been reported to co-operate with ER at DNA binding sites in breast cancer cells and to be positively associated with outcome in breast cancers receiving endocrine therapy." (PMID 33148314, 2020). "Interestingly, recent studies have highlighted the existence of mutations of RARA, independently from its fusions, in other conditions, including rare subtypes of breast cancers." (PMID 32295268, 2020). "We carried out immunoprecipitation assays to assess whether, firstly, there exists a direct or indirect association between RARα, the RXRα heterodimer and Sin3A in breast cancer cell lines and, secondly, whether MAD1-SID treatment would disrupt this interaction." (PMID 35406744, 2022). "For example, treatment of the transgenic mouse mammary tumor virus (MMTV)-Wnt1 breast cancer model with the RARα agonist Am580 inhibits the Wnt pathway and increases tumor-free survival." (PMID 41035698, 2025). "In fact, in culture of different breast cancer cell lines, RARα silencing impairs the anti-proliferative activity of ATRA." (PMID 38360674, 2024). "The observation is supported by ATRA-sensitivity studies performed on ER+ breast cancer cell lines and it is consistent with the demonstrated crosstalk between ERα (Estrogen Receptor alpha) and RARα." (PMID 38360674, 2024). "In its unliganded form, RARα is part of the ERα transcriptional complex and it contributes to the proliferative activity of estrogens in ER+ breast cancer cells." (PMID 38360674, 2024). "For instance, in some epithelial cells, including breast cancer cells and tumor associated fibroblasts, ATRA binding of plasma membrane RARα activates the p38MAPK (p38 Membrane Associated Protein Kinase)." (PMID 38360674, 2024). "The PML-RARA fusion gene is related to acute ovarian cancer, and RARA participates in estrogen signal transmission and is the target gene of estrogen in breast cancer." (PMID 35051904, 2022). "An in-silico analysis of “Kaplan–Meier plotter” database indicated that low PKCα together with high RARα mRNA expression is a favorable prognosis factor for hormone-independent breast cancer patients." (PMID 33723318, 2021). "For example, RARA binds cooperatively with ERα to regulate transcription at target sites within chromatin in breast cancers." (PMID 34215221, 2021). "RARA has been reported to promote tumor progression in breast cancer, acute promyeloid leukemia, and liver cancer." (PMID 35111672, 2021). "PITX1 has been reported in a breast cancer repressive complex that contains RARA, FOXA1, and ERα; identified prior to MegaTrans." (PMID 34215221, 2021). "RARA was found to be expressed in several breast cancer cell lines (e.g., the RARA-positive T47D breast cancer cell line)." (PMID 32823855, 2020). "Based on this threshold, RARA was expressed in all breast cancer cases, whereas RARG was detectable in less than 2% of cases in the METABRIC cohort." (PMID 33148314, 2020).
breast carcinoma (continued). "Nevertheless, TNBC-specific RARβ induction is the consequence of a retinoid-dependent activation of RARα, which is constitutively expressed in all types of breast cancer cells and it is the primary mediator of ATRA activity in mammary tumors." (PMID 33081033, 2020). "Alternatively, the opposite effects of RA on breast cancer cell growth were induced by either RARA or RAR gamma (RARG)." (PMID 32823855, 2020). "The anti-proliferative effect exerted by ATRA in sensitive breast cancer cell lines seems to be predominantly due to ligand-dependent activation of RARα." (PMID 33081033, 2020). "Breast cancers displaying RARA amplifications show sensitivity to retinoic acid and thus these subtypes of breast cancers can be treated with targeted therapies." (PMID 33167967, 2020). "Using the METABRIC breast cancer microarray dataset, we first examined the expression levels and degree of variance of MR, RARA, RARB and RARG in the cohort." (PMID 33148314, 2020). "The control exerted by S100A3 on RARα modulates the anti-tumor activity of ATRA in breast cancer SK-BR-3 and lung cancer A549 cells." (PMID 30532072, 2019). "RARA mRNA expression levels in breast cancer patients treated with hormonal therapy predicted positive outcome, which is in agreement with our findings." (PMID 31558802, 2019). "The involvement of CLs down-regulation and decreased assembly/function of mitochondria in the sensitivity of breast-cancer cells to ATRA is supported by the data obtained in RARα over-expressing and RARα knock-down cells." (PMID 31665044, 2019). "Induction of ATRA-resistance is consistent with the primary role exerted by RARα in mediating the anti-tumor action of the retinoid in breast cancer and the decrease in the levels of RARα afforded by S100A3 knockdown." (PMID 30532072, 2019). "The study reports on the identification of novel proteins interacting with RARα in breast cancer cells." (PMID 30532072, 2019). "In the present study, we define the basal and ATRA dependent RARα interactome in a RARα-overexpressing breast cancer cellular model, identifying 28 nuclear proteins." (PMID 30532072, 2019). "Cooperative interaction between RARα and ERα is reflected by the requirement for RARα for efficient ERα-mediated transcription and cell proliferation, as well as by its relationship with tamoxifen resistance in breast cancer." (PMID 30733805, 2019). "In breast-cancer, we identified RARα as the retinoid receptor mediating the growth-inhibitory activity exerted by ATRA." (PMID 31665044, 2019). "The degree of inhibition of RARα transcriptional function is variable in different breast cancer cell lines: mild in T47DCtrl, severe in T47DG303E, and extremely severe in T47D403." (PMID 31590252, 2019). "Given the key-role played by RARα in mediating ATRA anti-proliferative action in breast cancer cells, we also investigated the consequences of S100A3 silencing on ATRA-dependent growth inhibition of SK-BR-3 cells." (PMID 30532072, 2019). "Now, we know that ER drives the transcription of RARα and subsequently RARα drives the transcription of CRABP2 in ER+ mammary cancer cells." (PMID 31419991, 2019). "A significant fraction of HER2-positive breast carcinomas is characterized by co-amplification of the RARα gene, which leads to increased expression of the RARα protein and is associated with sensitivity to the antiproliferative action of RA." (PMID 29899874, 2018). "Interference with Sin3 function induces epigenetic reprogramming and differentiation in breast cancer cells through de-repression of E-cadherin, oestrogen receptor alpha (ERα) and retinoic acid receptor alpha (RARα)." (PMID 30552170, 2018). "The TFF1 gene was negatively correlated with the expression level for miR-200b in both breast cancer subtypes, meanwhile RARA gene was negatively correlated only in TNBC." (PMID 30342533, 2018). "RARα is also required for efficient estrogen receptor α mediated transcription and cell proliferation in breast cancer." (PMID 28035062, 2017).
breast carcinoma (continued). "In breast cancer, both AP-2 and RARα are able to drive CRABP-II expression through binding to the −5kb site of the promoter." (PMID 28881741, 2017). "In fact, activation of RARα has been shown to be sufficient for achieving retinoid response in both ER+ and ER–breast cancer cells while atRA, by activating PPAR β/δ, induced tumorigenic effects." (PMID 27286261, 2016). "As shown here by both genetic and pharmacological approaches, we discounted a role of PPARD in the T47D breast cancer cell context with maximal inhibition of RARA transcriptional function." (PMID 27894085, 2016). "Remarkably, also the cell context-specific degree of functionality of the RARA epigenetic component retained by breast cancer cells is critical to determine cell fate decisions in response to physiological as well as supraphysiological RA variation." (PMID 27894085, 2016). "We did also exclude that the mediator of ‘supraphysiological’ RA cancer-promoting action in breast cancer cells with inhibition of RARA transcriptional function is PPARD." (PMID 27894085, 2016). "In this study we provide evidence that both the anti-cancer and the cancer-promoting action of physiological RA in breast cancer have roots in a developmental RARA epigenetic mechanism of mammary epithelial cell fate." (PMID 27894085, 2016). "The breast cancer cell context-specific RARA transcriptional functionality seems to be critical for determining cell fate decisions in response to ‘supraphysiological’ RA variation." (PMID 27894085, 2016). "Overall, this study supports the proof of concept that RA breast cancer-promoting action has roots in a cell-autonomous RARA epigenetic mechanism of mammary morphogenesis." (PMID 27894085, 2016). "In this study, we traced both anti-cancer and cancer-promoting actions of physiological and supraphysiological RA in breast cancer cells to the plasticity of a RARA epigenetic mechanism of normal mammary epithelial cell morphogenesis." (PMID 27894085, 2016). "Since breast cancer is a disease related to aging, not only mutations, but also deterioration of breast tissue per se might be a factor capable of negatively affecting the epigenome of breast epithelial cells by weakening the transcriptional functionality of RARA." (PMID 27894085, 2016). "There is in vivo mechanistic evidence that preventing physiological RA from activating wild type RARA transcriptional function in the mammary gland induces typical breast cancer features, such as aberrant ductal morphology and excessive cell proliferation." (PMID 27894085, 2016). "Given the observed relevance of the RARα3 transcript in our models, the basal levels of the corresponding RARα protein were determined in breast cancer cell lines with a specific antibody (Fig8A and B)." (PMID 25888236, 2015). "In summary, our findings demonstrate that ATRA-induced autophagy is mediated by RARα in breast cancer cells." (PMID 26313912, 2015). "In the present study, we report that ATRA induces autophagic flux in retinoid-sensitive SKBR3 breast cancer cells via RARα." (PMID 26313912, 2015). "In contrast to their study, where depleting RARα induced 3-MA-sensitive autophagy, our results in differentiation-competent breast cancer cells show that RARα depletion abrogates 3-MA-sensitive proteolysis." (PMID 26313912, 2015). "The association between RARA rearrangements and HER2-amplified breast cancer was also seen in a recent study." (PMID 26439695, 2015). "This apparent parallel response suggests a cooperative interaction of RARα and AP-1 using T47D breast cancer cells." (PMID 26462767, 2015). "Gene cluster B contained ERα and a group of NRs previously associated with ERα in breast cancer, including PGR, AR, RARα, LRH-1, PNR, as well as TRβ, RORβ, and RORγ." (PMID 26280373, 2015). "Using 3-MA as a specific inhibitor of macroautophagy, we were able for the first time to directly link macroautophagy induction to RARα activation in breast cancer cell lines." (PMID 26313912, 2015).
breast carcinoma (continued). "The amplification of the retinoic acid receptor α (RARα) and retinoic acid sensitivity were found to correlate to breast cancer progression." (PMID 25520935, 2014). "We found that over-expressing c-Myc in normal mouse mammary epithelium and in a c-Myc-driven transgenic model of mammary cancer, disrupts the balance between RARγ and RARα/β in favor of RARγ." (PMID 22920668, 2012). "Treatment of MMTV-Myc mice with the RARα-selective agonist Am580 led to significant inhibition of mammary tumor growth (~90%, P<0.001), lung metastasis (P<0.01) and extended tumor latency in 63% of mice." (PMID 22920668, 2012). "The basal expression of RARα1, the only RARα isoform that was expressed in breast cancer cell lines and in most breast tumors, was supported by apo-ER but was unaffected by OH-Tam; RAR-β and -γ were not regulated by apo-ER." (PMID 21299862, 2011). "RARα subtype expression was also examined in breast cancer cell lines and tumors by competitive PCR." (PMID 21299862, 2011). "The functional RARα isoform in different hormone-sensitive breast cancer cell lines and that identified in a limited number of breast tumors was almost exclusively of type 1, an isoform that is believed to be genetically redundant." (PMID 21299862, 2011). "Previous studies using breast cancer cell lines have suggested that selective stimulation of RARβ increases NIS expression more efficiently than that of RARα." (PMID 21283523, 2011). "Because wnt1 pathway activation is involved in human breast cancer, and RARα has a proven role in breast cancer, the mechanism connecting RARα1 to control of wnt-tumorigenicity is worthy of further study." (PMID 20923554, 2010). "Our published work, showed that chronic treatment of MMTV-wnt1 mice with the same RARα agonist inhibited mammary tumor formation and growth." (PMID 20923554, 2010). "All-trans retinoic acid (ATRA), the most potent naturally occurring metabolite of vitamin A, reversibly inhibits the growth of hormone-dependent human breast cancer cells, requiring the activation of RARα-mediated gene transcription for this effect." (PMID 15505623, 2004). "The region of chromosome 17q amplified in CALU3 also includes the retinoic acid receptor alpha locus and is therefore similar to the amplicon observed in breast cancers carrying amplified topoisomerase II alpha and retinoic acid receptor sequences." (PMID 8398710, 1993). "Finally, the role played by RARα in mediating the anti-proliferative action of ATRA in breast cancer is supported by studies performed with RARα specific agonists." (PMID 38360674, 2024). "Indeed, RARα is known to be a direct ERα target gene, which is induced upon estrogen treatment of breast cancer cells." (PMID 38360674, 2024). "Furthermore, melatonin has been shown to enhance the transcriptional activity of RARα and its binding to RAREs in breast cancer cells." (PMID 36672220, 2023). "However, when RA is unavailable, or cells become resistant to RA, RARα activation occurs via Erα receptors, thus triggering cell proliferation and tumor metastasis in breast cancer progression." (PMID 37645246, 2023). "However, another study reported that PKCα overexpression promotes RARα expression levels in breast cancer cells following ATRA treatment, and increased RARα leads to ATRA sensitization through AP1 trans-repression." (PMID 36358843, 2022). "In addition, another study indicated that RARα promotes the interaction of estrogen receptor coactivators and participates in estrogen-induced gene transcription in breast cancer cells." (PMID 34858481, 2021). "Among RAR subunits, RARα is the principal mediator of RA responsiveness in breast cancer." (PMID 33902658, 2021). "Low PRKCA mRNA expression was statistically associated with a best RFS of breast cancer patients with negative estrogen receptor tumors (HR = 1.36, p = 0.027), while RARA mRNA expression did not affect RFS probability." (PMID 33723318, 2021).
breast carcinoma (continued). "In addition, we demonstrated that the anti-proliferative action exerted by ATRA in breast cancer cells is mediated by RARα." (PMID 32384653, 2020). "Similarly, in an evaluation of 42 breast cancer cell lines representative of the breast cancer heterogeneity, RARα was found as the major mediator of ATRA sensitivity." (PMID 32012980, 2020). "Indeed, the presence of RARα over-expression in breast cancer overlapped with sensitivity to retinoic acids." (PMID 32012980, 2020). "RARα is the major determinant of ATRA anti-tumor activity in breast cancer." (PMID 30532072, 2019). "Furthermore, recent reports have indicated that RARα can present in membrane lipid rafts and form complexes with Gαq after RA stimulation, and that the formation of RARα/Gαq complexes is suppressed in RA-resistant breast cancer cells." (PMID 29312596, 2017). "We determined that subtype-specific expression of this tumor suppressor is due to both its specific hypomethylation, and ALDH1A3 expression within basal-like breast cancers, which provides its necessary transcription induction molecule, RA, for nuclear hormone receptor RARα." (PMID 27286452, 2016). "Consistently, breast cancer cells without RARA mutations, but with epigenetic signs of functional inhibition of RARA transcriptional activity, form tumors under in vivo physiological RA conditions." (PMID 27894085, 2016). "Molecular signs of a dysfunctional RARA mechanism have been detected in breast cancer tissue." (PMID 27894085, 2016). "Moreover, according to CIDER the AP-1complex, together with the IRF1 TF, promotes the expression of RARA, linking theErbB pathway activation to the suppression of estrogen receptor activity, shown inthe more aggressive phenotypes of breast cancer." (PMID 26179713, 2015). "The antiproliferative, cytodifferentiating and proapoptotic effects of retinoids are predominantly mediated by the nuclear hormone retinoid acid receptors RARα, RARβ and RARγ.13, 14 In breast cancer, preclinical studies have shown that retinoids are promising therapeutic agents." (PMID 26313912, 2015). "Given the observation that both RARA agonist and antagonist actions show benefit on breast cancer, both mechanisms of action might be taking place." (PMID 23192763, 2013). "Given the significant differences in structure and regulation between the two RARα isoforms it was of interest to determine whether only one or both isoforms were relevant in the regulation of RARα by apo-ER in breast cancer cells." (PMID 21299862, 2011). "This hypothesis was bolstered by the fact that this SNP lies less than 1 kb away from a retinoic acid receptor α (RARA) binding site detected by ChIP-chip in the breast cancer cell line MCF-7." (PMID 21060808, 2010). "Thus, partially repressed RARα/β expression may explain the minimal clinical activity using retinoids such as ATRA as a single agent in breast cancer treatment." (PMID 35406744, 2022). "Breast cancer is not characterized by RARA structural mutations." (PMID 30678048, 2019). "Thus, the breast cancer cell context-specific transcriptional functionality of the RARA mechanism, not only differentially affects the epigenetic state of RARA-target genes, but also determines cancer-promoting effects of physiological RA synthesis due to the level of ALDH activity." (PMID 27894085, 2016). "Based on these findings, breast cancer cell fate decisions seem to depend on how the biological effects of RARA-mediated transcriptional regulation of direct target genes keep in check the cancer-promoting effects of RARA-mediated activation of PI3K effectors in response to RA variation." (PMID 27894085, 2016). "In the breast cancer model represented by MCF10A cells, RARα overexpression disrupts the normal acinar structure of the 3D cultures, inducing features of the EMT status." (PMID 38360674, 2024).